GHR (growth hormone receptor)
Diseases named in the same sentence as GHR in open-access papers (continued):
Sharing a sentence is not in itself a finding about the gene and the disease.
Hypoglycemia (continued). "Nevertheless, it would be interesting to study lymphocyte proliferation in older GHR-KO pigs as well, independent of hypoglycemia." (PMID 37189345, 2023). "A similar lymphocyte percentage in GHR-KO and WT pigs suggests that reduced GHR signaling and hypoglycemia did not affect the development of lymphocytes in the bone marrow and thymus." (PMID 37189345, 2023). "Future studies should investigate IFN-α levels in older GHR-KO pigs independent of hypoglycemia." (PMID 37189345, 2023). "Furthermore, since these cells are highly dependent on glucose, the purpose of this study was to investigate how the absence of GHR signaling and prolonged hypoglycemia affect the development of the immune system in GHR-KO pigs." (PMID 37189345, 2023). "Therefore, a GHR-KO pig model characterized by low IGF1 levels and juvenile hypoglycemia was used." (PMID 37189345, 2023). "Therefore, further experiments, such as functional assays investigating the substrate preferences of WT and GHR-KO PBMCs would be necessary to confirm or reject a difference in the metabolism of GHR-KO CD4+ PBMCs and possible compensatory mechanisms towards hypoglycemia." (PMID 37189345, 2023). "GHR-KO pigs show important hallmarks of the human disease, including reduced levels of insulin-like growth factor 1 (IGF1) and IGF-binding protein 3 (IGFBP3), increased serum GH concentrations, postnatal growth retardation, juvenile hypoglycemia, and a progressive increase in total body fat." (PMID 33029223, 2020).
malnutrition (8 papers, 2015 to 2023). Inadequate nutrition resulting from poor diet, malabsorption, or abnormal nutrient distribution. "In mammals, starvation can decrease GHR levels while malnutrition such as protein deficiency rather appears to inhibit the post-GHR signaling pathways." (PMID 29867764, 2018). "GHR studies in pigs revealed that the abundance of GHR mRNA increased in the longissimus dorsi during mild postpartum malnutrition." (PMID 36634654, 2023). "Litters were weaned at week 3, and muscle specific GHR expression was assessed for the next three weeks based on optimal or low food intake, resulting in the expression of the GHR gene and its regulation in mild malnutrition." (PMID 36634654, 2023). "Previous studies demonstrated the rapid development of GH resistance along with a decrease in GHR during malnutrition." (PMID 25909895, 2015). "We wanted to verify whether GHR gene expression plays a role in the growth failure of children with CD, as a result of the chronic inflammatory condition and malnutrition." (PMID 30483486, 2018). "Accordingly, the effects of malnutrition, as observed during severe cases of IBD or SBS, potentially impacts GHR expression negatively." (PMID 28486400, 2017). "In conclusion, oral administration of leucine improved GH resistance in rats with malnutrition by promoting IGF-1, reducing IGF-1 degradation, and facilitating GHR synthesis in the liver." (PMID 25909895, 2015). "It has been described that malnutrition could change the GH-IGF-1 pathway by producing GH resistance, inhibiting hepatic expression of GHR, and IGF-1 mRNA, as well as precipitating the disintegration, and reducing the bioactivity of IGF-1." (PMID 36374927, 2022).
Glucose intolerance (7 papers, 2011 to 2023). Glucose intolerance (GI) can be defined as dysglycemia that comprises both prediabetes and diabetes. "The simultaneous disruption of GHRH and GHR genes resulted in dramatically decreased body weight, higher insulin sensitivity, and glucose intolerance." (PMID 33755309, 2021). "This non‐intuitive glucose intolerance with insulin sensitivity may be due to low β‐cell mass, leading to impaired effects of glucose clearance, which is also seen in GHR knockout models." (PMID 33755309, 2021). "When glucose was administered by i.p. injection, GHR KO pigs exhibited glucose intolerance." (PMID 34803486, 2021). "In sum, expression of the RIP::IGF-1 transgene partially corrected glucose intolerance, rescued insulin sensitivity, partially ameliorated the aberrantly heightened gluconeogenic production, and reduced fasted blood glucose content in female GHR-KO mice." (PMID 25244225, 2014).
liver cancer (7 papers, 2012 to 2024). An epithelial or non-epithelial malignant neoplasm that arises from the liver. "Jin-Wu Nam at Hanyang University and Suk Woo Nam at The Catholic University of Korea, both in Seoul, South Korea, identified two isomiRs associated with liver cancer; these isomiRs incorrectly targeted the growth hormone receptor, suppressing its expression." (PMID 35729324, 2022). "Through Reactome enrichment analysis, it was seen that liver cancer caused changes in biological oxidation reactions and conjugation ability to metal ions (phase II-conjugation of compounds, metallothioneins bind metals and response to metal ions) and also affected growth hormone receptor signaling." (PMID 34238253, 2021). "Treatment with antagomirs against isomiR-21-5p | ±1 inhibited the in vitro tumorigenesis of liver cancer cells and allowed the recovery of GHR, whereas the introduction of isomiR-21-5p | ±1 mimics attenuated these effects." (PMID 35729324, 2022). "Liver cancer patients with high GHR expression showed better overall prognosis and longer relapse-free survival." (PMID 35729324, 2022). "miR-21–5p suppresses growth hormone receptor (GHR) in liver cancer." (PMID 37958999, 2023). "It has been reported that GHR is expressed in colorectal and liver cancers." (PMID 23554765, 2012). "On the basis of the expression of the newly edited and generated ED_miR-3144(3_A < G) target gene was reduced as liver cancer progressed, five candidates, INMT, GHR, GLYAT, SLC38A4, and HMGCS2, were identified through target prediction and expression pattern analyses." (PMID 36599932, 2023). "In particular, GHR was most repressed in liver cancer compared to its expression in non-tumor tissues." (PMID 35729324, 2022).
cognitive decline (6 papers, 2016 to 2025). "GHR’s association with cognitive decline was confirmed in the Replication Cohort (HR 3.6 [95% CI 1.20–11.1, p = 0.02])." (PMID 31603904, 2019). "In analyses of longitudinal data, we showed that baseline levels of ACY1 and GHR—and, to a lesser extent, OMD—associated with subsequent rates of cognitive decline in our Discovery Cohort, with baseline GHR predicting subsequent cognitive course in the Replication Cohort as well." (PMID 31603904, 2019). "Snell dwarf (DW) and growth hormone receptor knockout (GKO) mice show delays in age‐dependent cognitive decline." (PMID 35930768, 2022). "In particular, we have identified four plasma proteins—BSP, OMD, ACY1, and GHR—with consistent alterations in PD, one of which (GHR) also predicted subsequent cognitive decline in multiple cohorts, across multiple cognitive testing instruments." (PMID 31603904, 2019). "We found that lower GHR levels at baseline predicted a faster rate of cognitive decline in people with PD." (PMID 31603904, 2019). "We hypothesize that GHR and SLC19A3 genes might act either as genetic modifiers that exacerbate the severity of cognitive decline induced by the primary disease-causing mutation in the MAN2B1 gene or as additional disease loci co-segregating with AM." (PMID 34614013, 2021). "Moreover, despite differences in cognitive scale and clinical site used, as well as stage of PD assessed (all factors known to affect measures of cognition over time), lower levels of GHR also predicted faster cognitive decline in the Replication Cohort." (PMID 31603904, 2019). "Accordingly, riluzole-induced reduction in extracellular glutamate levels could prevent hippocampal cognitive decline in aged rats and improved memory retrieval in aged growth hormone receptor knockout mice was correlated with decreased hippocampal glutamate levels." (PMID 35181756, 2022). "Because cognitive symptoms are less affected by dopaminergic medication than motor symptoms, and because decline in cognition is variable but clinically important in PD, we investigated whether baseline levels of BSP, OMD, ACY1, or GHR predicted subsequent rates of cognitive decline." (PMID 31603904, 2019). "Fourth, we note that baseline levels of GHR, ACY1, and, to a lesser extent, OMD predicted future cognitive decline in individuals with PD from the Discovery Cohort." (PMID 31603904, 2019). "In the prior behavioral literature, stress is reported as an inducer of local GH synthesis in the CNS, while GH expression in aging is purported to have a negative effect insofar as aged GHR knock-out mice avoid a cognitive decline that becomes manifest in wt animals." (PMID 26894278, 2016).
Hypertension (6 papers, 2012 to 2025). The presence of chronic increased pressure in the systemic arterial system. "Stratification analysis of GHR fl/d3 polymorphism with height, BMI, hypertension, and metabolic traits by region was performed." (PMID 35402349, 2022). "In girls, GHR d3 allele was associated with increased odds of pre-hypertension and hypertension, and ORs (95% CIs) for the additive model were 1.379 (1.106-1.719) and 1.240 (1.013-1.519) with P-values of 0.004 and 0.037, respectively." (PMID 35402349, 2022). "Interaction of GHR fl/d3 polymorphism with gender contributed to increased odds of pre-hypertension and hypertension (interactive ORs [95% CIs]: 1.735 [1.214-2.481], P = 0.003; OR [95% CI]: 1.509 [1.092-2.086], P = 0.013)." (PMID 35402349, 2022). "Breslow-Day test showed significant interactive effects of GHR fl/d3 polymorphism and gender on pre-hypertension and hypertension risk existed, and the P-values of the homogeneity test were 0.002 and 0.013, respectively." (PMID 35402349, 2022). "GHR d3 allele is found to be associated with decreased odds of pre-hypertension and hypertension in boys, while increased odds of pre-hypertension and hypertension in girls was observed." (PMID 35402349, 2022). "We observed the multiplicative interaction of GHR fl/d3 polymorphism with gender contributing to increased odds of pre-hypertension and hypertension and found that GHR d3 allele was likely to have a protective effect against high TC level." (PMID 35402349, 2022). "Conversely, GHR d3 allele was associated with increased odds of pre-hypertension and hypertension in Yixing girls (ORs [95% CIs] for the additive model: 1.366 [1.055-1.770], P = 0.018; 1.273 [1.009-1.606], P = 0.042)." (PMID 35402349, 2022). "In the current study, we investigated the associations of GHR fl/d3 polymorphism with height, BMI, hypertension, and metabolic traits in healthy children and adolescents with the largest sample size." (PMID 35402349, 2022). "Boys with GHR d3 allele were associated with decreased odds of pre-hypertension, and ORs (95% CIs) for the additive model and dominant model were 0.791 (0.645-0.971) and 0.777 (0.609-0.990) with P-values of 0.025 and 0.042, respectively." (PMID 35402349, 2022). "Logistic regression was used to evaluate the associations of GHR fl/d3 polymorphism with height, BMI, metabolic traits, and hypertension by estimating the odds ratios (ORs) and 95% confidence intervals (CIs)." (PMID 35402349, 2022). "We propose that in individuals with hypertension, longevity-associated genetic variation in GHR enhances cell resilience mechanisms to help protect against cellular stress caused by hypertension." (PMID 34074802, 2021). "A UK study found an association of the longevity-associated GHR exon 3 deletion variant with hypertension amongst stroke patients." (PMID 34074802, 2021). "The overall association of genetic variation in GHR with mortality risk was contributed entirely by genotype-dependent amelioration of the increased mortality risk from hypertension." (PMID 34074802, 2021). "This indicated that possession of the GHR longevity-associated genotype can mitigate the adverse effects on lifespan of having hypertension." (PMID 34074802, 2021). "As a result, hypertension-affected men who possess the longevity-associated genetic variant of GHR live as long as normotensive men." (PMID 34074802, 2021). "Association analysis of GHR fl/d3 polymorphism with pre-hypertension and hypertension." (PMID 35402349, 2022). "GHR fl/d3 polymorphism is associated with growth, metabolism, and hypertension in children and adolescents with the gender specificity, and the genetic effect of GHR fl/d3 may be modified by the local socioeconomic levels." (PMID 35402349, 2022). "Our study was aimed to evaluate whether GHR fl/d3 polymorphism was associated with growth, metabolic traits, and hypertension risk with a relatively large healthy children and adolescent population." (PMID 35402349, 2022).
Hypertension (continued). "In conclusion, the current study demonstrated that GHR fl/d3 polymorphism was associated with BMI, metabolism, and hypertension in children and adolescents, which may be modified by local socioeconomic levels." (PMID 35402349, 2022). "GHR d3 allele was associated with decreased odds of pre-hypertension in boys (OR [95% CI]: 0.791 [0.645-0.971], P = 0.025), but associated with increased odds of pre-hypertension and hypertension in girls (ORs [95% CIs]: 1.379 [1.106-1.719], P = 0.004; OR [95% CI]: 1.240 [1.013-1.519], P = 0.037)." (PMID 35402349, 2022). "Furthermore, interaction between GHR fl/d3 polymorphism and gender on pre-hypertension and hypertension was first illustrated, suggesting genetic effects of this polymorphism may have a gender specificity." (PMID 35402349, 2022). "Other GHR SNPs – rs6182, rs6180, rs6184 (minor allele frequencies 0.137, 0.387, 0.077) that are non-synonymous (amino acid changes Cys440Phe, Leu544Ile and Pro579Thr, respectively) – have been found to be associated with hypertension and elevated blood pressure in Japanese men." (PMID 34074802, 2021). "These curves were determined using a Cox proportional hazard model adding an interaction term of GHR with hypertension." (PMID 34074802, 2021). "Hazard ratios (HR) of homozygotes (AA, GG) vs. heterozygotes (AG) of GHR SNP, rs4130113, with total mortality in men by hypertension status." (PMID 34074802, 2021). "No statistical associations of GHR d3 polymorphism with pre-hypertension or hypertension were observed in total subjects." (PMID 35402349, 2022). "In conclusion, men without hypertension lived the longest, while, in the group with hypertension, those homozygous for either the major (common) or minor (less common) allele of GHR SNP rs4130113 lived longer than those who were heterozygous for this SNP." (PMID 34074802, 2021). "In studies of FOXO3, MAP3K5, PIK3R1, GHR, and FLT1 we found that for each, the genetic variants associated with longer lifespan may activate cell resilience mechanisms, leading to amelioration of the adverse effects of hypertension." (PMID 37561089, 2023). "First, potential confounding factors, such as calorie intake and physical exercise, that may introduce bias by modifying the associations between GHR fl/d3 polymorphism, BMI, metabolic traits, and hypertension were not examined." (PMID 35402349, 2022). "Threshold effect analysis of GHR and gallstones stratified by BMI, ALT, and hypertension." (PMID 39950129, 2025).
colorectal cancer (5 papers, 2012 to 2021). A primary or metastatic malignant neoplasm that affects the colon or rectum. "The protective effect of GH on radiation in radiated GHR-expressing human colorectal cancer cell HCT-8 treated with hGH or GHR antibody has been demonstrated on the basis of cell survival rate and DNA damage detection." (PMID 34178997, 2021). "Combining recombinant GH with radiation increases clonogenic survival and reduces DNA damage in a colorectal cancer cell line, whereas the over-expression of GHR in rectal cancer is predictive factor for tumor response to preoperative radiotherapy." (PMID 34178997, 2021). "GHR-expressing human colorectal cancer cells HCT-8, pretreated with different doses of recombinant hGH, showed a dose-dependent increase in post-irradiation survival while comet assays exhibited reduced DNA damage." (PMID 32382711, 2019). "The RNA expression of CSC markers like CD24, CD44, NANOG, SALL4, and POU5F1 were also exclusively observed in GHR-expressing subsets of the colorectal cancer cells." (PMID 32382711, 2019). "Nuclear localization of GHR and increased GHR levels have been reported in breast and colorectal carcinoma." (PMID 31939481, 2019). "It has been previously demonstrated that growth hormone receptor (GHR) was expressed in human colorectal cancer and some other cancers." (PMID 23554765, 2012).
growth failure (5 papers, 2012 to 2023). "Chronic inflammatory diseases in children are associated with growth failure and muscle wasting, which may result from the suppression of growth hormone receptor (GHR) expression by pro‐inflammatory cytokines." (PMID 37323108, 2023). "Although these growth deficiencies are likely multifactorial in etiology, the growth hormone (GH)-growth hormone receptor (GHR) interactions that recruit JAK kinase and stimulate phosphorylation of STAT5B remain intact, suggesting a breakdown in corresponding STAT5B activity." (PMID 31717342, 2019). "Interestingly, a growth deficiency phenotype of GHR-KO pigs was observed no earlier than postnatal week 5, which indicated that GH was not required as promoter of intrauterine and early postnatal growth." (PMID 29678421, 2018).
growth hormone insensitivity syndrome (5 papers, 2011 to 2021). Growth hormone insensitivity syndrome (GHIS) is a group of diseases characterized by marked short stature associated with normal or elevated growth hormone (GH) concentrations, which fail to respond to exogenous GH administration. "Furthermore, heterozygous mutations in the GHR gene identified in patients with Growth Hormone Insensitivity Syndrome (GHIS) were also correlated with MR in 13.5% of the studied cohort." (PMID 34614013, 2021). "STAT5B plays a key role downstream of the IL2 receptor and the growth hormone receptor (GHR), explaining why STAT5B defect causes Growth hormone insensitivity syndrome (GHIS) with a complex infectious and somatic phenotype." (PMID 30671054, 2018).
lung carcinoma (5 papers, 2018 to 2021). "Two independent studies showed that a single-nucleotide polymorphism in GHR resulting in a P495T substitution was associated with lung cancer." (PMID 33312162, 2020). "The link between GHR signaling and lung cancer has been shown in two independent genetic studies that identified an SNP in GHR that correlated with an increased risk of lung cancer." (PMID 29487568, 2018). "The importance of SOCS2-mediated degradation of GHR has recently been underscored by a study showing that this was the key mechanism that causes an increased risk of developing lung cancer in individuals that carry an SNP in GHR resulting the in the amino acid change P495T in the GHR ICD." (PMID 29487568, 2018). "It was shown that protein expression levels of chemokine CXCL16 which regulates inflammation, growth hormone receptor (GHR) and PRL were elevated in lung tumor tissue, which was associated with decreased survival of patients with lung cancer." (PMID 34487971, 2021).
metabolic syndrome (5 papers, 2011 to 2025). A cluster of metabolic risk factors for CARDIOVASCULAR DISEASES and TYPE 2 DIABETES MELLITUS. "Both patients with Y-derived-material had primary amenorrhea, dyslipidemia and reached the height of 150 cm despite not treated with recombinant growth hormone (GHr)." (PMID 34762780, 2021).
pituitary adenomas (5 papers, 2016 to 2023). "We then demonstrated that the GHR is expressed both at the mRNA and protein levels in human GH-secreting pituitary adenomas." (PMID 27267119, 2016). "Reassuringly, the experience from more than 10-year use of pegvisomant is that GHR-targeted therapy does not induce growth of pituitary adenomas." (PMID 29789410, 2018).